IL13 (interleukin 13)
Diseases named in the same sentence as IL13 in open-access papers (continued):
Sharing a sentence is not in itself a finding about the gene and the disease.
asthma (continued). "The effects of IL-13 in promoting enhanced Cmu infection demonstrated in the current study may provide a basis for the widely observed clinical and experimental link between chlamydial infection and asthma." (PMID 21573182, 2011). "Antagonising the function of IL-13 in asthma may be a therapeutically effective strategy." (PMID 20064211, 2010). "That the increased accumulation of IL-13+ T cells was observed in female but not male asthmatics, and the association was maintained when analysis was restricted to only atopic subjects, indicates that the effect was a function of asthma and not atopy per se." (PMID 20667106, 2010). "Increased production of IL-4 and IL-13 in both CD4+ and CD8+ T cells accompanied by decreased IFN-γ expression in CD4+ T cells may be evidence that both lymphocyte subpopulations are implicated in the pathogenesis of asthma." (PMID 21197090, 2010). "Moreover, IL-13 levels in the airways correlated with disease severity in children and degree of airway hyperresponsiveness in adult asthma subjects, which may correspond well with our findings." (PMID 21197090, 2010). "Interestingly, in an animal model of asthma niflumic acid, a relatively specific blocker of calcium-activated chloride channel, inhibits IL-13-induced goblet cell hyperplasia, MUC5AC expression, airway hyperresponsiveness, BAL eosinophilia and eotaxin increase." (PMID 18315837, 2008). "Furthermore, most forms of asthma are characterized by abundant Th2 cytokine secretion (e.g IL-4, 5, 9 and, in particular, IL-13), and the over-expression of these cytokines in transgenic mouse models has been shown to reproduce numerous features of asthma including subepithelial fibrosis." (PMID 18348727, 2008). "In an animal model of asthma intratracheally delivered AP-1 decoy oligodeoxynucleotides attenuate eosinophilic airway inflammation, airway hyperresponsiveness, mucous cell hyperplasia, production of allergen-specific immunoglobulins, and synthesis of IL-4, IL-5, and IL-13 in the lung." (PMID 18315837, 2008). "Hence, IL-13 may contribute to subepithelial fibrosis in asthma by stimulating biologically significant TGF-β2 secretion from the airway epithelium." (PMID 18348727, 2008). "In addition, soluble IL-13Rα2 is effective in blocking the actions of IL-13, including IgE production, pulmonary eosinophilia and airway hyperresponsiveness in animal models of asthma and humanised IL-13Rα2 is now entering phase I clinical trials in asthma." (PMID 18315837, 2008). "Interaction analysis between IL-4/IL-13 and their shared receptor is of particular interest because gene-gene interactions may modify the effects of individual SNPs in the IL-4/IL-13 pathway, and evidence of epistasis has been reported in a asthma and type 1 diabetes." (PMID 18625055, 2008). "Macrophages treated with Th2-type cytokines such as Interleukin-4 (IL-4) and Interleukin-13 (IL-13) exhibit an altered phenotype and such alternatively activated macrophages are important in the pathology of diseases characterised by allergic inflammation including asthma and atopic dermatitis." (PMID 17134490, 2006). "In asthma mouse models, early RSV infection has also been shown to exacerbate airway inflammation and enhance Th2 cytokine expression, including IL-4 and IL-13." (PMID 41576028, 2026). "Using a house dust mite (HDM)-induced murine asthma model and HDM, IL-4, IL-13, or TNF-α stimulated human primary bronchial epithelial cells (BECs) and bronchial epithelial (Beas-2b) cells, we modulated FAO with L-carnitine (agonist) and Etomoxir (inhibitor)." (PMID 41555513, 2026). "In a previous study, WEIF was revealed to reduce the serum levels of Th2 cytokines (IL-4, IL-5, and IL-13) and IgE in an OVA-induced asthma model by inhibiting the JAK/STAT signaling pathway." (PMID 40806199, 2025).
asthma (continued). "The main molecular pathways of asthma include T2 inflammation, mediated by Th2 and ILC2 cells, eosinophils, and the cytokines IL-4, IL-5, and IL-13, as well as non-T2 inflammation, mediated by neutrophils, macrophages, and the cytokines IL-1, IL-6, and IL-17." (PMID 40136501, 2025). "The relevance between the FEO‐03 network and asthma on the KEGG Pathways database presented EPX, IL4, IL5, IL13, CD40LG, TNF, and IL10 according to p value." (PMID 40777200, 2025). "Conversely, hypomethylation of proinflammatory genes, including iNOS, IL-13, and CXCL8, can promote their overexpression, further amplifying airway inflammation and asthma severity." (PMID 40806756, 2025). "In asthma, epithelial exposure to allergens (dust mite proteases and pollen) induces IL‐33/TSLP, driving ILC2‐mediated IL‐13 production that increases airway epithelial permeability and goblet cell metaplasia." (PMID 40679787, 2025). "Given that males with asthma were found to have more type 2 cells (ILC2s) but less alarmin cytokines (TSLP) and type 2 cytokines (IL‐13) compared to females, we explored the role of miRNAs as an additional modulator of the immune response." (PMID 40022441, 2025). "Recently, it was demonstrated that mainly IL-13 induces CCL11 and CCL24 in fibroblasts and monocytes, which was required for eosinophil attraction in HDM-induced murine asthma." (PMID 40276331, 2025). "In contrast, increased levels of IL‐13, TSLP and sST2 were found in females with asthma compared with males." (PMID 40022441, 2025). "In an acute OVA model of asthma in TSLP/TSLPR humanized mice, TAVO101 reduces total serum IgE, lung TARC, IL-13, and eosinophil accumulation similarly to a benchmark anti-TSLP." (PMID 41409758, 2025). "We showed how this BsAb potently neutralized signaling from TSLP, IL-4, and IL-13; reduced inflammatory responses in human cell-based assays; and provided broader efficacy in a TSLP/OVA-induced asthma model compared with single-pathway blockade." (PMID 41294800, 2025). "This is consistent with previous work showing that elevated TSLP in lungs correlates with increased AHR in both mouse models and human asthma, and that neutralizing TSLP or downstream cytokines like IL-4 and IL-13 mitigates AHR and airway inflammation." (PMID 41259396, 2025). "A systems pharmacology approach has identified the capacity of baicalin to target 48 asthma-related genes such as IFNγ, IL4, IL5, IL10, IL13, and TNFα and signaling pathways, reinforcing its polypharmacological properties." (PMID 40598285, 2025). "In T2-high asthma, eosinophilic inflammation and IL-13-mediated smooth muscle changes contribute to AHR, whereas in T2-low asthma, factors such as neutrophil-mediated inflammation, oxidative stress, and epithelial dysfunction play a more significant role." (PMID 40508095, 2025). "We examined the correlations of serum IL-36 levels with serum IL-6, IL-8, IL-10, IL-13, IL-17, IFN-γ, and TNF levels, except for IL-4 and IL-5 levels, which were only rarely observed in our asthma patients." (PMID 40115968, 2025). "Galectin-9 has demonstrated efficacy in a Dermatophagoides farinae allergen-induced asthma model by suppressing the expression of IL5, IL13, CCL11, CCL17, reducing eosinophilia, and pulmonary hyperresponsiveness." (PMID 41516283, 2025). "The following studies demonstrated compromised epithelial barriers in conditions like asthma, atopic dermatitis (AD), and CRS, exposure to barrier‐toxic substances, and the effects of type 2 immune responses, particularly cytokines IL‐4 and IL‐13." (PMID 40679787, 2025). "In asthma patients, including Th2 cell transcription factor, GATA3 the high levels of Th2-cell related cytokines such as IL-4, IL-5 and IL-13 were observed." (PMID 40323927, 2025). "In asthma and atopic dermatitis, PAH exposure correlates with Th2-biased cytokine expression and epigenetic modifications at loci such as IL4 and IL13." (PMID 41020825, 2025).
asthma (continued). "In the experiment, after OVA stimulation, the levels of IL-4, IL-5, IL-13, and TNF-α in BALF and the level of IgE in the serum of mice in the asthma model group were significantly elevated, indicating that Th2 cells were overly active." (PMID 40563981, 2025). "Oral administration of L. reuteri ATCC 23272 also resulted in immunoregulatory effects, with elevated IL-10 levels and reduced levels of IL-5, IL-13, MCP-1, and TNF-α in OVA-induced asthma mice." (PMID 39820222, 2025). "In a more mechanistic approach, using mice that only lack IL-4/IL-13 in T cells, our group showed that cytokines of Th2 cells are responsible for induction of eosinophilia in OVA-induced asthma as well as in an ABPA mouse model." (PMID 40276331, 2025). "Central to the eosinophilic inflammation seen in many asthma phenotypes are TH2 lymphocytes, which secrete IL-4, IL-5, and IL-13 in large amounts." (PMID 40732309, 2025). "In the HDM mouse model of asthma, SM17 reduced lung pathology score, eosinophil infiltration, and inflammatory cytokine (IL-4, IL-5, IL-13) secretion to levels comparable to dexamethasone-treated mice." (PMID 41409758, 2025). "The targets of the FEO‐03 network, IL13, and functional partners IL13RA1, IL13RA2, IL4R, IL6, and TNF were presented in a red box from the asthma diagram of KEGG Pathways." (PMID 40777200, 2025). "Lunsekimig (anti-IL-13/anti-TSLP) is a nanobody that blocks both IL-13 and TSLP and is currently included in a phase II clinical trial for moderate-to-severe asthma (AIRCULES)." (PMID 40364184, 2025). "Results showed that KIF1B expression was markedly elevated in bronchial biopsies from asthma patients, OVA‐challenged mouse lungs and IL‐13–stimulated BEAS‐2B cells." (PMID 41384344, 2025). "Reduced ACE-2 expression in the airways of asthma patients may limit viral entry into cells, and the Th2 immune response, prominent in allergic diseases like atopic asthma, could suppress the pro-inflammatory Th1 response via the type 2 cytokines IL-4 and IL-13, offering further protection." (PMID 40004141, 2025). "This suggests that IL-5 may synergize with other cytokines such as IL-4 and IL-13 that are known to have a fibrotic by stimulating airway fibroblasts, further exacerbating airway remodelling, positioning it as a potential therapeutic target for fibrosis-related complications in asthma." (PMID 41188935, 2025). "Airways from individuals with severe asthma showed increased MTOR signaling by RPS6 phosphorylation, which was reproduced using an IL-13–activated model of primary human airway epithelial cells (hAEC)." (PMID 40446022, 2025). "IL‐4 and IL‐13, together with TGF‐β, stimulate the production of periostin, which then promotes fibroblast differentiation and EMT in asthma." (PMID 40777200, 2025). "These conclusions were reflected in the animal asthma model (ovalbumin-treated mice), as CBD therapy led to a decrease of IgE, IL-4, IL-5, and IL-13 levels in both blood and lung tissue, as well as eosinophil and neutrophil infiltration in the lung." (PMID 40244178, 2025). "It is interesting that the level of IFN‐γ remained relatively stable compared with the varying levels of IL‐4, IL‐5, and IL‐13, despite a slight increase in the number of Th1 cells and level of IFN‐γ in the lungs during acute asthma exacerbation." (PMID 38938285, 2024). "In the ovalbumin-induced rat asthma model, FXR reduces airway inflammation by preventing inflammatory cell infiltration and inhibiting IL-4, IL-5, and IL-13 secretion, likely through antagonizing NFκB signaling and its target genes." (PMID 39411430, 2024). "Given the importance of IL-13 to the state of the epithelium, serum IL-13 level could potentially be considered a biomarker of epithelial health if it could be assessed in routine clinical practice, although it may lack specificity given its wide-ranging role in asthma pathophysiology." (PMID 39694589, 2024).
asthma (continued). "For example, in type 2-high asthma, TH2 cells and ILC2s are significant IL-4, IL-5, and IL-13 sources; furthermore, infiltrating mast cells, eosinophils, and basophils play vital roles in producing type 2 cytokines." (PMID 39439788, 2024). "IL-13 is a cytokine secreted by Th2 cells, ILC2, and NKT and is known to be secreted in large quantities in diseases such as asthma and atopic dermatitis." (PMID 38732497, 2024). "Key molecular pathways of refractory asthma include T2 inflammation mediated by Th2 and ILC2 cells, eosinophils, and cytokines including IL-4, IL-5, and IL-13." (PMID 39194521, 2024). "The concentrations of cytokines such as IL-4, IL-5, IL-13, and TSLP in serum, sputum, and bronchoalveolar lavage fluid (BALF) in asthma have been reported to range from 1 to 100 pg/ml (approximately 0.7–70 pM)." (PMID 39624446, 2024). "In the experiments presented here, we used the MMWR to explore how IL-13, a key cytokine mediator of HAEC dysfunction in asthma, mediates the formation of pathologic mucus gels." (PMID 38889046, 2024). "Administration of crocin (25 mg/kg/day, PO) in mice with asthma induced by OVA resulted in a decrease in levels of TNF-α, IL-4, IL-13, LDH, and MDA, while levels of SOD and GSH in lung tissue were increased." (PMID 38419885, 2024). "In TSLP/OVA induced asthma model, the intranasal administration of TSLP/OVA significantly induced the elevation of serum IgE level and key inflammatory cytokines CCL17 and IL-13 levels in the lung which contributed to the disease establishment and progression." (PMID 39726595, 2024). "It is plausible that these recruited NK cells, now differentiated as NK2 cells, will produce cytokines including IL-4, IL-5, and IL-13 and lower antiviral cytokine IFN-γ, leading to asthma exacerbations." (PMID 38216935, 2024). "Our results have shown that the increased expression of CTSC also promoted the infiltration of inflammatory cells and the production of inflammatory factors (e.g., IL-5, IL-13, and IL-17A) in the HDM-induced asthma model and SA model." (PMID 39436705, 2024). "Prior studies have shown that IL-13 regulates TPO expression in airway epithelial cells and that patients with asthma have high TPO expression in their bronchial epithelial brushings." (PMID 38889046, 2024). "ER stress induced by IL‐13 increases MUC5AC expression in airway epithelial cells, and an inhibitor of ER stress partially attenuates MUC5AC expression in asthma." (PMID 39365189, 2024). "IL-4 and IL-13 also directly induce the production of FENO, which is commonly used as a predictive factor for exacerbation recurrence in asthma, but it isn’t considered in most CRSWNP guidelines." (PMID 38850424, 2024). "With regard to asthma, a blockade of TL1A with neutralizing antibodies suppressed airway inflammation and levels of IL-4, IL-5, and IL-13 in a murine model of asthma." (PMID 38540714, 2024). "We found that the mRNA expression of IL-13, TNF, IL-4, VEGFR2 and VEGF, were downregulated in the control, dexamethasone and vandetanib groups compared with the asthma group." (PMID 38799165, 2024). "Targeting IL-13 and GATA-3 provides a potential therapeutic approach, given their significant roles in the exacerbation of asthma symptoms." (PMID 38903705, 2024). "In COPD and asthma samples, we found an increased number of MUC5AC-positive cells (goblet cell metaplasia), consistent with elevated exposure to IL-13." (PMID 39255033, 2024). "Then, we assessed the levels of IgE, Th2 cytokines (IL-4, IL-5, and IL-13), eotaxin, TGF-β1, and MUC5AC using ELISA kits to detect the effect of scutellarin on the release of asthma-related cytokines in ovalbumin-challenged mice." (PMID 38168709, 2024). "Patients with T2-high asthma consistently show an increased production of MUC5AC, a process mediated by both IL-13 and epidermal growth factor." (PMID 39694589, 2024).
asthma (continued). "The majority of asthma sufferers present with a type 2 inflammatory response and profile characterised by hyper-production of IL4, IL5, and IL13, increased blood eosinophils and fractional exhaled nitric oxide (FeNO)." (PMID 38529406, 2024). "ILC2s release type 2 cytokines (such as IL-5 and IL-13) and growth factors (such as AREG) in inflamed and injured lung tissues in patients with chronic obstructive pulmonary disease and asthma." (PMID 39405112, 2024). "Candida albicans aggravate Th2‐mediated asthma and reduce AHR through the IL‐13‐IL‐33 axis after infection." (PMID 38687096, 2024). "The CC genotypes of IL4rs2243250, IL6 rs1800795, IL13 rs1800925, as well as theGG genotype of TNFA rs1800629 were shown in our study tobe protective against the development of mild asthma." (PMID 37465198, 2023). "IL-13 stimulation decreases ACE2 mRNA and protein levels in human primary airway epithelial cells derived from asthma patients." (PMID 37608279, 2023). "Estrogens and progesterone affect the immune response and pathogenesis of asthma, airway hyperresponsiveness, and type 2 inflammation involving eosinophils, ILC2, IL-13, and IL-5." (PMID 37629446, 2023). "12/15-LOX has been shown to be reciprocally regulated by IL-13 (increases) and IFN-γ (decreases), suggesting that 12/15-LOX functions as an immunopathogenic factor in type 2/Th2 high asthma." (PMID 37253655, 2023). "In vivo, Lok effectively protected mice from asthma, as evidenced by decreased histological damage and level of cytokines in BALF (IL-4, IL-13 and TGF-β1) by 17%–77%." (PMID 37655452, 2023). "They observed a reduction in the blood levels of IL-4, IL-5, IL-13, and monocyte chemoattractant protein-1 (MCP-1) and an improvement in bronchial hyperreactivity (BHR) and FEV1." (PMID 36873818, 2023). "Therefore, IL-4 and IL-13 levels may be potential predictors of asthma in children with wheezing." (PMID 37760982, 2023). "In an experimental asthma model, it was revealed that NKT cells express TSLPR and IL-7 receptor, and TSLP was shown to directly act on NKT cells and induce the production of IL-13 and thus to increase airway hyperactivity." (PMID 37108740, 2023). "Protein-protein network analysis demonstrated that ANXA1 interacts directly with genes enriched for asthma (including IL4 and IL13) and inflammatory regulation (NR3C1, glucocorticoid receptor) showing its significance in dysregulation of the immune response." (PMID 37227431, 2023). "Vitamin E and selenium have been shown to affect Th2 cytokines (IL-4, IL-5, and IL-13) as well as their upstream cytokines (IL-25 and IL-33), suggesting that they may be a beneficial treatment for the management of allergic diseases such as allergic rhinitis and asthma." (PMID 37513609, 2023). "For the interleukin-13 (IL-13) transgenic (TG) C57BL/6 mouse model, asthma was induced by lung-specific IL-13 overexpression." (PMID 37110362, 2023). "In the present study, there was an increase in the inflammatory markers involved, such as IL-1β, IL-4, IL-5, IL-6, IL-10, IL-13, IL-17, IFN-γ, and TNF-α, in the experimental model of asthma-COPD overlap." (PMID 37511021, 2023). "Further investigation of the biological function of ANXA1 revealed that it interacts with genes enriched for asthma (including IL4 and IL13) and inflammatory regulation (NR3C1, glucocorticoid receptor)." (PMID 37227431, 2023). "Patients with CRSwNP and comorbid asthma demonstrate IgE-mediated release of immune mediators and upregulation of type 2 cytokines (IL-4, IL5, and IL-13) in the upper and lower airways." (PMID 37464395, 2023). "We also detected levels of oxidative stress markers (MDA, CAT and SOD), and frequent inflammation cytokines (IL-4, IL-5 and IFN-γ) in IL-13-induced BEAS-2B cells and BALF fluid of asthma mice." (PMID 36788676, 2023). "Autophagy was shown as a central contributor to IL-13-mediated mucus hypersecretion by airway epithelial cells in COPD and asthma." (PMID 37251385, 2023).